HACL2 (2-hydroxyacyl-CoA lyase 2)
Description:
Endoplasmic reticulum 2-OH acyl-CoA lyase involved in the cleavage (C1 removal) reaction in the fatty acid alpha-oxydation in a thiamine pyrophosphate (TPP)-dependent manner. Involved in the phytosphingosine degradation pathway.
Synonyms: AHAS; ILVBL; 209L8; ILV2H; MGC1269; FLJ39061; MGC19535; HACL1L
Tractability: Antibody: UniProt predicts a signal peptide or a membrane-spanning region. PROTAC: ubiquitination databases record sites on it; its protein half-life has been measured.
Target class: Enzyme; Lyase
Gene: Protein-coding gene on chromosome 19 (15,114,976 to 15,125,792, reverse strand). Ensembl gene ENSG00000105135.
Subcellular location: Endoplasmic reticulum membrane
Subcellular location (Human Protein Atlas): Golgi apparatus; Vesicles
Gene Ontology:
Molecular function: protein binding; flavin adenine dinucleotide binding; catalytic activity; magnesium ion binding; thiamine pyrophosphate binding
Biological process: fatty acid alpha-oxidation
Cellular component: endoplasmic reticulum membrane; membrane; acetolactate synthase complex
Genetic constraint (gnomAD): Loss-of-function variants: 45 observed, 62.41 expected, observed/expected ratio (o/e) 0.72, 90% interval 0.57 to 0.92. The upper end of that interval is the gene's LOEUF score, 0.92, which puts it in group 3 of 6, group 1 being the genes least tolerant of losing a copy. Missense variants: 786 observed, 857.4 expected, observed/expected ratio (o/e) 0.92, 90% interval 0.86 to 0.97. Synonymous variants: 332 observed, 363.17 expected, observed/expected ratio (o/e) 0.91, 90% interval 0.83 to 1.
Homologues: Orthologues: chimpanzee ILVBL (99% identical), macaque ILVBL (93% identical), guinea pig ILVBL (89% identical), pig ILVBL (88% identical), rat Ilvbl (88% identical), dog ILVBL (87% identical), mouse Ilvbl (86% identical), rabbit ILVBL (86% identical), zebrafish ilvbl (64% identical), tropical clawed frog ilvbl (64% identical), Caenorhabditis elegans T26C12.1 (55% identical). Paralogues in human: HACL1 (25% identical).
Diseases named in the same sentence as HACL2 in open-access papers:
HACL2 is named in the same sentence as 10 diseases in open-access papers, as found by Europe PMC text mining. Sharing a sentence is not in itself a finding about the gene and the disease. The quoted sentences say what the papers report.
diabetes (2 papers, 2024 to 2025). "In a mouse model of diabetes, ilvb acetolactate-synthase-like (ILVBL, HACL2) is the enzyme involved in formation of increased amounts of dimethylglyoxal from lactate-derived pyruvate." (PMID 38987239, 2024).
Thiamine deficiency (1 paper, 2017). Thiamine deficiency is a condition that occurs due to not enough thiamine (vitamin B1). "Given that both HACL1 and HACL2 are dependent on thiamine-pyrophosphate, one could expect an effect of thiamine deficiency on odd-chain fatty acids, but thiamine deficiency is currently very rare in Western countries." (PMID 29027957, 2017).
HACL2 also shares sentences with these, for which no sentence is quoted: aspergillosis (1 paper); asthma (1); cancer (1); Intellectual disability (1); learning disability (1); microcephaly (1); neurodegenerative disease (1); respiratory disease (1).